PITRM1 (pitrilysin metallopeptidase 1)
Description:
Metalloendopeptidase of the mitochondrial matrix that functions in peptide cleavage and degradation rather than in protein processing. Has an ATP-independent activity. Specifically cleaves peptides in the range of 5 to 65 residues. Shows a preference for cleavage after small polar residues and before basic residues, but without any positional preference. Degrades the transit peptides of mitochondrial proteins after their cleavage. Also degrades other unstructured peptides. It is also able to degrade amyloid-beta protein 40, one of the peptides produced by APP processing, when it accumulates in mitochondrion. It is a highly efficient protease, at least toward amyloid-beta protein 40. Cleaves that peptide at a specific position and is probably not processive, releasing digested peptides intermediates that can be further cleaved subsequently. It is also able to degrade amyloid-beta protein 42.
Synonyms: hMP1; KIAA1104; MP1; PREP; SCAR30
Tractability: Small molecule: a structure with a bound ligand is known. PROTAC: ubiquitination databases record sites on it; its protein half-life has been measured; a small molecule that binds it is known.
Target class: Enzyme
Gene: Protein-coding gene on chromosome 10 (3,137,728 to 3,172,841, reverse strand). Ensembl gene ENSG00000107959.
Subcellular location: Mitochondrion; Mitochondrion matrix
Subcellular location (Human Protein Atlas): Mitochondria
Pathways (Reactome):
Protein localization: Mitochondrial protein import
Gene Ontology:
Molecular function: metalloendopeptidase activity; metallopeptidase activity; zinc ion binding; enzyme activator activity; metal ion binding
Biological process: proteolysis; protein localization to mitochondrion
Cellular component: mitochondrial matrix; mitochondrion
Genetic constraint (gnomAD): Loss-of-function variants: 73 observed, 88.97 expected, observed/expected ratio (o/e) 0.82, 90% interval 0.68 to 1. The upper end of that interval is the gene's LOEUF score, 1, which puts it in group 4 of 6, group 1 being the genes least tolerant of losing a copy. Missense variants: 1,131 observed, 993.46 expected, observed/expected ratio (o/e) 1.14, 90% interval 1.08 to 1.2. Synonymous variants: 472 observed, 400.12 expected, observed/expected ratio (o/e) 1.18, 90% interval 1.09 to 1.27.
Homologues: Orthologues: chimpanzee PITRM1 (99% identical), macaque PITRM1 (98% identical), rabbit PITRM1 (89% identical), mouse Pitrm1 (87% identical), rat Pitrm1 (85% identical), guinea pig PITRM1 (84% identical), dog PITRM1 (82% identical), pig PITRM1 (79% identical), tropical clawed frog pitrm1 (74% identical), zebrafish pitrm1 (67% identical), Drosophila melanogaster CG3107 (38% identical). Paralogues in human: NRDC (15% identical), IDE (13% identical), PMPCB (10% identical), UQCRC1 (9% identical), PMPCA (9% identical), UQCRC2 (9% identical).
Diseases named in the same sentence as PITRM1 in open-access papers:
PITRM1 is named in the same sentence as 32 diseases in open-access papers, as found by Europe PMC text mining. Sharing a sentence is not in itself a finding about the gene and the disease. The quoted sentences say what the papers report.
Alzheimer disease (11 papers, 2020 to 2025). A progressive, neurodegenerative disease characterized by loss of function and death of nerve cells in several areas of the brain leading to loss of cognitive function such as memory and language. "We dissect distributional regulatory effects at established Alzheimer’s Disease (AD) risk genes including PITRM1, TMEM106B, and the CHRNE/SCIMP/RABEP1 cluster, revealing complex context-dependent regulatory architecture missed by linear analysis." (PMID 41377971, 2025). "At Alzheimer’s disease (AD) risk loci, qQTL analysis revealed complex regulatory architecture including variance effects at PITRM1, lower-quantile-specific effects at TMEM106B partially explained by APOE ε4 interactions, and coordinated epigenetic regulation at loci harboring CHRNE/SCIMP/RABEP1." (PMID 41377971, 2025). "Interestingly, besides mitochondrial presequences, PITRM1 also degrades Aβ peptides, which are associated with Alzheimer’s disease pathology and can accumulate in mitochondria, where they perturb mitochondrial function and induce neuronal death." (PMID 35388015, 2022). "PITRM1 was associated with amyloidogenic neuropathy and Alzheimer’s disease." (PMID 32508873, 2020). "scRNA‐seq of pitrilysin metallopeptidase 1 (PITRM1)‐knockout iPSCs spontaneously developed brain organoids showed pathological features of Alzheimer's disease (AD)." (PMID 38115706, 2023). "On the other hand, over time, cerebral organoids generated from PITRM1-knockout iPSCs spontaneously developed pathological features of Alzheimer’s disease (AD), including the accumulation of protein aggregates, tau pathology, and neuronal cell death." (PMID 32632204, 2021). "Further it was proved that PITRM1 LOF induces proteotoxic stress and Alzheimer’s disease-like pathology in human cerebral organoids." (PMID 33445687, 2021).
cognitive decline (7 papers, 2016 to 2023). "We have recently described patients from three unrelated families carrying pathogenic variants in PITRM1, resulting in progressive spinocerebellar ataxia, obsessional behaviour, and cognitive decline." (PMID 37576821, 2023). "We identified two siblings carrying a homozygous PITRM1 missense mutation (c.548G>A, p.Arg183Gln) associated with an autosomal recessive, slowly progressive syndrome characterised by mental retardation, spinocerebellar ataxia, cognitive decline and psychosis." (PMID 26697887, 2016). "We have recently reported that pathogenic variants in the nuclear-encoded mitochondrial peptidase PITRM1 result in childhood-onset recessive cerebellar disease characterized by spinocerebellar ataxia, mild intellectual disability, psychiatric manifestations, and cognitive decline." (PMID 32632204, 2021). "Mutations in pitrilysin metallopeptidase 1 (PITRM1), a mitochondrial protease involved in mitochondrial precursor processing and degradation, result in a slow-progressing syndrome characterized by cerebellar ataxia, psychotic episodes, and obsessive behavior, as well as cognitive decline." (PMID 32632204, 2021). "PITRM1 participates in the processing and degrading of mitochondrial precursors and amyloid β; it is an important enzyme because altering it results in incremental cognitive decline, psychotic episodes, and cerebellar ataxia." (PMID 37106802, 2023). "PITRM1 may be a potential therapeutic target for halting AD progress as well as age‐related dementia and cognitive decline by clearance of accumulation of toxic metabolites in mitochondria and maintenance of mitochondrial integrity." (PMID 33951271, 2021).
spinocerebellar ataxia (7 papers, 2016 to 2023). "We have recently discovered that recessive PITRM1 pathogenic variants are associated with a slowly progressive syndrome characterized by spinocerebellar ataxia, intellectual disability, impaired cognition and psychosis." (PMID 37576821, 2023). "Loss-of-function variants in human PITRM1 result in a childhood-onset progressive amyloidotic neurological syndrome characterized by spinocerebellar ataxia with behavioral, psychiatric and cognitive abnormalities." (PMID 33835239, 2021). "We recently found that recessive PITRM1 mutations are associated with a slowly progressive syndrome characterized by mental retardation, spinocerebellar ataxia, cognitive decline and psychosis." (PMID 34356897, 2021). "A Pitrm1+/− heterozygous mouse showed progressive ataxia associated with brain degenerative lesions, including accumulation of Aβ‐positive amyloid deposits." (PMID 26697887, 2016). "Thus, robust evidence shows that PITRM1 deficiency due to biallelic variants leads to progressive neurological impairment including ataxia, mental retardation and psychiatric features, and an overall susceptibility to neurodegeneration." (PMID 34356897, 2021).
amyloid (3 papers, 2020 to 2021). "The intraneuronal punctuate amyloid accumulation and neurological phenotype in humans, mice and dogs confirm the role of PITRM1 in the clearance of amyloid and the neurodegeneration that develops if the clearance fails." (PMID 33835239, 2021). "Notably, the present findings show that an efficient enhancement of PITRM1-mediated brain proteostasis can be accomplished with a nutraceutical intervention, which deserves to be investigated for its potential role in preventing and/or reducing amyloid pathology." (PMID 32848778, 2020).
autosomal recessive spinocerebellar ataxia (2 papers, 2024 to 2025). "Mutations in human pitrilysin metallopeptidase 1 (PITRM1), a mitochondrial matrix enzyme, are linked to autosomal recessive spinocerebellar ataxias (ARCA) that occur in early childhood." (PMID 40801612, 2025). "PITRM1 biallelic mutations have been linked to autosomal recessive spinocerebellar ataxia and may participate in cancer cell survival mediated by linear noncoding RNA SNHG5." (PMID 39835009, 2024).
autosomal recessive spinocerebellar ataxia 30 (2 papers, 2025). "Pathogenic mutation of PITRM1 is associated with autosomal recessive spinocerebellar ataxia-30 (SCAR30, MIM #619405), largely characterised by progressive spinocerebellar ataxia, cerebellar atrophy, early-onset developmental delay and psychosis." (PMID 40857737, 2025). "Among these, three were OMIM-annotated:ZMYND11 (associated with autosomal dominant intellectualdevelopmental disorder 30 [AD]), WDR37 (linked toneurooculo-cardiogenitourinary syndrome [AD]), PITRM1(implicated in autosomal recessive spinocerebellar ataxia 30[AR])." (PMID 40995453, 2025).
neuropathy (2 papers, 2012 to 2021). A disorder affecting the nervous system that manifests with pain, tingling, numbness, and/or muscle weakness. "The mutational disruption of electrostatic interactions in proximity of PITRM1 residue R183 contributes to the loss of enzyme activity and may contribute to the loss-of-function phenotype observed in PITRM1 R183Q-dependent neuropathy." (PMID 34356897, 2021).
Adult onset (1 paper, 2021). Onset of disease manifestations in adulthood, defined here as at the age of 16 years or later. "Importantly, although human PITRM1 mutations are relatively rare, the disease mechanisms described in the present study may apply to both primary mitochondrial diseases and more common adult-onset neurological diseases." (PMID 32632204, 2021).
anemia (1 paper, 2023). A reduction in the number of red blood cells, the amount of hemoglobin, and/or the volume of packed red blood cells. "Analysis of a gene expression dataset from PITRM1-deficient or sufficient organoids also revealed statistically significant changes in anemia-like processes." (PMID 36979320, 2023).
epilepsy (1 paper, 2021). A brain disorder characterized by episodes of abnormally increased neuronal discharge resulting in transient episodes of sensory or motor neurological dysfunction, or psychic dysfunction. "Our study describes a novel early-onset PITRM1-related neurodegenerative canine brain disorder with mitochondrial dysfunction, Aβ accumulation, and lethal epilepsy." (PMID 33835239, 2021).
Epileptic encephalopathy (1 paper, 2021). A condition in which epileptiform abnormalities are believed to contribute to the progressive disturbance in cerebral function. "In summary, we describe a novel mitochondrial neurodegenerative disease with epileptic encephalopathy and demonstrate defective PITRM1 as the cause." (PMID 33835239, 2021). "Our study sets up a novel canine model of PITRM1-related neurodegenerative disease with a mitochondrial respiratory deficiency and severe epileptic encephalopathy." (PMID 33835239, 2021).
glioma (1 paper, 2023). A benign or malignant brain and spinal cord tumor that arises from glial cells (astrocytes, oligodendrocytes, ependymal cells). "PITRM1 belongs to metallopeptidase and has been reported to be associated with hypoxia and glucose deprivation in glioma cells." (PMID 37363401, 2023).
medulloblastoma (1 paper, 2020). A malignant, invasive embryonal neoplasm arising from the cerebellum. "For Group 4 medulloblastomas, B naïve cells were positively correlated with RUNX2 (p = 0.031, r = 0.208) and PITRM1 (p = 0.025, r = 0.214) expression, and the latter was negatively correlated with memory B cells as well (p = 0.048, r = −0.198)." (PMID 32508873, 2020).
Onset (1 paper, 2021). The age group in which disease manifestations appear. "To address these questions, we have generated a novel human stem-cell-based model of the loss of PITRM1 function that recapitulates several pathological aspects of human PITRM1-related mitochondrial and adult-onset neurodegenerative diseases." (PMID 32632204, 2021).
neurodegenerative disease (5 papers, 2016 to 2022). A disorder of the central nervous system characterized by gradual and progressive loss of neural tissue and neurologic function. "In summary, we have identified a human neurodegenerative disease combining impaired motor coordination, cognitive and psychotic features, caused by a hypomorphic pathogenic mutation in the mitochondrial protease PITRM1 associated with protein instability." (PMID 26697887, 2016). "PITRM1 deficiency leads to mitochondrial unfolded protein response and enhanced clearance, a defect associated with various neurodegenerative diseases underlying a novel mitochondrial-related neurodegenerative phenotype associated with β-amyloid protein accumulation." (PMID 34440765, 2021). "Genome-wide genetics reveal that DELE1 additionally responds to compromised presequence processing by the matrix proteases PITRM1 and MPP, which are mutated in neurodegenerative diseases." (PMID 35388015, 2022). "The variant is an in-frame 6-bp deletion in pitrilysin metallopeptidase 1 (ENSCAFT00000008673 c.175_180del), a known neurodegenerative disease gene." (PMID 33835239, 2021).
mitochondrial disease (1 paper, 2021). "In conclusion, we report a novel cellular model of human PITRM1 deficiency that recapitulates several fundamental pathological aspects of PITRM1-related mitochondrial disease." (PMID 32632204, 2021).
PITRM1 also shares sentences with these, for which no sentence is quoted: infection (5 papers); psychosis (4); cancer (2); cerebellar ataxia (2); Intellectual disability (2); neurological diseases (2); amyotrophic lateral sclerosis (1); arrhythmogenic right ventricular dysplasia 5 (1); Ataxia (1); bacterial infections (1); brain disorder (1); Charcot-Marie-Tooth disease (1); conduct disorder (1); movement disorder (1); status epilepticus (1); tumour (1).